CREB1 (cAMP responsive element binding protein 1)
Diseases named in the same sentence as CREB1 in open-access papers (continued):
Sharing a sentence is not in itself a finding about the gene and the disease.
osteoarthritis (7 papers, 2015 to 2025). A noninflammatory degenerative joint disease occurring chiefly in older persons, characterized by degeneration of the articular cartilage, hypertrophy of bone at the margins and changes in the synovial membrane. "The DSCR1-1/CREB1/ALDH2/Wnt/β-catenin axis has been demonstrated to be involved in the etiology of osteoarthritis." (PMID 40968356, 2025). "During the progression of osteoarthritis, down syndrome candidate region 1–1 (DSCR1-1) can inhibit chondrocyte apoptosis by regulating the cAMP-responsive element protein 1 (CREB1)/ALDH2/Wingless and int-1 (Wnt)/β-catenin axis." (PMID 40968356, 2025).
cholangiocarcinoma (6 papers, 2016 to 2025). A carcinoma that arises from the intrahepatic biliary tree (intrahepatic cholangiocarcinoma) or from the junction, or adjacent to the junction, of the right and left hepatic ducts (hilar cholangiocarcinoma). "Our in silico analysis revealed that a total of six TFs (SP1, CREB1, MAX, FHL2, RFX1 and HIF1A) were upregulated in cholangiocarcinoma tissues." (PMID 34199886, 2021). "Moreover, expressions of six TF genes (SP1, CREB1, MAX, FHL2, RFX1, and HIF1A) was positively correlated with the expression of ITGA6 and ITGB1 in cholangiocarcinoma tissues." (PMID 34199886, 2021).
cocaine addiction (6 papers, 2013 to 2025). "The differences between sexes in the expression of cocaine addiction genes such as CREB1 and protein kinases such as PRKACB have been previously reported in mice under other experimental conditions." (PMID 35627199, 2022). "Among up- and downregulated genes from the pathway hsa05030:cocaine addiction are genes JUN, GNAS, BDFN, and CDK5R1 (upregulated), and FOSB, NFKB1, CREB1 and PPP1R1B (downregulated)." (PMID 34947877, 2021).
prion disease (6 papers, 2008 to 2023). A transmissible disease that is caused by a protein that is able to induce abnormal folding of normal cellular proteins, leading to characteristic spongiform brain changes, which are associated with neuronal loss without an inflammatory response. "EGR1 has been shown to share a disproportionate number of transcriptional targets with CREB1, also down-regulated in prion disease, suggesting that these two may be functionally related." (PMID 18987751, 2008).
esophageal cancer (5 papers, 2019 to 2023). A primary or metastatic malignant neoplasm involving the esophagus. "Similar to our results, Xu and colleagues reported that CREB1 can be used as a predictor of the prognosis of esophageal cancer." (PMID 33921660, 2021). "Imperatorin also directly targets CREB1 to inhibit TGFβ2-ERK signaling and inhibit esophageal cancer metastasis." (PMID 33921660, 2021).
liver disease (5 papers, 2021 to 2025). "It was observed that AR, CREB1, ACVR2A, and CXCL12 were down-regulated in T1DM-associated liver disease; however, they exhibited up-regulation after NAC treatment." (PMID 40001479, 2025). "Also, the analysis of the reactome of SLC19A1 revealed its direct relation to the core transcription factor CREB1, which has been proposed as a potential therapeutic target for liver disease." (PMID 36830876, 2023). "CAMP response element-binding protein 1 (CREB1) is a core transcription factor, and it may be a promising therapeutic target for liver diseases." (PMID 36836704, 2023).
lymph node metastasis (5 papers, 2014 to 2023). "In GC, CREB1 was overexpressed and correlated with lymph node metastasis, distant metastasis and poor prognosis." (PMID 30674866, 2019). "And further analysis showed that the RRM2 and CREB1 staining was positively correlated with lymph node metastasis, distant metastasis and advanced TNM stages (p<0.05)." (PMID 27801665, 2016). "CREB1 expression was found to be significantly positively correlated with lymph node metastasis (P = 0.0002), distant metastasis (P = 0.0007), and tumor stage (P = 0.008)." (PMID 25825983, 2015). "Using similar quantitative proteomics approaches, we have previously identified serum protein biomarkers for classification of oral cancer patients with lymph node metastasis and revealed that the cAMP response element-binding protein 1 (CREB1) pathway is activated in oral cancer stem-like cells." (PMID 25196439, 2014).
myeloproliferative disease (5 papers, 2009 to 2024). "Transgenic mice of CREB1 developed myeloproliferative disease, while knockdown of CREB1 impaired proliferation of HSC and AML cells, indicating the critical role of CREB1 in myeloid cell proliferation." (PMID 39015025, 2024).
myoepithelioma (5 papers, 2014 to 2022). "FISH studies, performed to rule out the possibility of gastrointestinal clear cell sarcoma and a myoepithelial tumor, showed no rearrangement of the EWSR1, FUS, ATF1, and CREB1 genes." (PMID 35001360, 2022).
psoriasis (5 papers, 2021 to 2022). An autoimmune condition characterized by red, well-delineated plaques with silvery scales that are usually on the extensor surfaces and scalp. "For example, SNP rs58726213 is associated with psoriasis and is ASB of CREB1 (reference allele preference, concordant with motif) and JUN (alternative allele preference)." (PMID 33980847, 2021). "In psoriasis uninvolved skin, positive correlations were found between the expression levels of CREB1 and LEF1 (r = 0.66, p < 0.05), USF1 and PNOC (r = 0.81, p < 0.05), MITF and ATRN (r = 0.58, p < 0.05), MITF and NURR1 (r = 0.56, p < 0.05) and MITF and MAPK14 (r = 0.75, p < 0.01)." (PMID 34884858, 2021). "CREB1 mRNA expression in psoriasis lesional skin was 4.9-fold lower (p < 0.001) and in non-lesional skin of psoriasis patients it was 6.3-fold lower (p < 0.001) when compared to healthy control skin." (PMID 34884858, 2021).
pulmonary hypertension (5 papers, 2013 to 2025). Increased pressure within the pulmonary circulation due to lung or heart disorder. "However, others had reported reduced CREB1 expression in pulmonary vascular smooth muscle following sustained lung hypoxia and suggested that a consequent reduction in CREB1 activity played a key role in pulmonary vascular remodeling and pulmonary hypertension." (PMID 24349008, 2013).
Rett syndrome (5 papers, 2017 to 2022). A severe neurodevelopmental disorder affecting the central nervous system. "Individuals with a 2q33.4-q34 interstitial deletion have ASD and other symptoms observed in Rett syndrome, and this deletion includes CREB1." (PMID 30498565, 2018).
glaucoma (4 papers, 2021 to 2025). Increased pressure in the eyeball due to obstruction of the outflow of aqueous humor. "ROC curves suggested that miR-106-5p-CAPZA2/CREB1 axis and miR-15a-5p-SLC2A3 axis (AUC > 0.9) exhibited excellent ability to distinguish POAG from non-glaucoma individuals." (PMID 37940950, 2023).
HIV-1 infection (4 papers, 2016 to 2022). The type species of lentivirus and the etiologic agent of acquired immunodeficiency syndrome (AIDS). "In addition, cAMP responsive element binding protein 1 (CREB1) and its target genes identified by the recombinant canarypox vector ALVAC + Alum could augment immunogenicity and reduce the HIV-1 infection rate." (PMID 35923698, 2022).
Hodgkin's disease (4 papers, 2008 to 2022). "However, in Hodgkin lymphoma, CREB1 was found to be tumor suppressive by regulating key aspects of cell proliferation." (PMID 32300145, 2020).
ischemic heart disease (4 papers, 2016 to 2022). "Among the genes, 1-hop and 2-hop neighbors in the underlying network, were chromatin licensing and DNA replication factor 1 (CDT1), minichromosome maintenance complex component 5 (MCM5), and cAMP-responsive element-binding protein 1 (CREB1), which have been linked to ischemic heart disease before." (PMID 35903362, 2022).
malignant glioma (4 papers, 2016 to 2019). A grade III or grade IV glioma arising from the central nervous system. "Currently, only one report has demonstrated that miR-1224 inhibited tumor-associated activity in malignant gliomas by targeting cAMP response element-binding protein (CREB1)." (PMID 31019895, 2019). "miR-1224-5p has been shown to act as a tumor suppressor by targeting CREB1 in malignant gliomas." (PMID 31681214, 2019).
meningioma (4 papers, 2012 to 2024). A generally slow growing tumor attached to the dura mater. "With respect to downstream gene sets of PI3K/Akt pathway, proliferation-promoted genes such as CTNNB1, CREB1, CREB5, and TCF7L2 were up-regulated in fibroblastic meningioma." (PMID 23285163, 2012).
pancreatic adenocarcinoma (4 papers, 2021 to 2022). "Based on the TCGA database results, the expression levels of CREB1, PTEN, SMAD3, and CASP3 genes are up-regulated in the pancreatic adenocarcinoma." (PMID 34155232, 2021). "Later, using TCGA data, we realized that the expression of PTEN, CREB1, CASP3, and SMAD3 are significantly (|Log FC| ≥ 1 and p value < 0.01 as the cut-off criteria) increased in Pancreatic adenocarcinoma (PAAD) (data not shown)." (PMID 34155232, 2021).
pancreatic ductal adenocarcinoma (4 papers, 2019 to 2025). An infiltrating adenocarcinoma that arises from the epithelial cells of the pancreas.
atrial fibrillation (3 papers, 2016 to 2025). A disorder characterized by an electrocardiographic finding of a supraventricular arrhythmia characterized by the replacement of consistent P waves by rapid oscillations or fibrillatory waves that vary in size, shape and timing and are accompanied by an irregular ventricular response. "In this study, integrative bioinformatics analysis revealed that infarct-mediated overexpression of potential miR-662/CREB1 pathway-induced neuropeptide VIP may be associated with the risk of atrial fibrillation." (PMID 34853624, 2021). "The decreased expression of miR-425-5p in atrial fibrillation (AF) results in elevated levels of CREB1, promoting atrial fibrosis and remodeling." (PMID 40417179, 2025).
chronic obstructive pulmonary disease (3 papers, 2018 to 2024). A chronic and progressive lung disorder characterized by the loss of elasticity of the bronchial tree and the air sacs, destruction of the air sacs wall, thickening of the bronchial wall, and mucous accumulation in the bronchial tree. "Elevated CREB1 activity has been linked by many studies to the regulation of proinflammatory cytokines production and to the pathogenesis of respiratory diseases such as chronic obstructive pulmonary disease (COPD)." (PMID 30257479, 2018).
colon adenocarcinoma (3 papers, 2017 to 2024). "By analyzing the GEIPA-COAD (colon adenocarcinoma) and READ (rectum adenocarcinoma) database, expression levels of CREB1 and HNF4A were found to be significantly higher in colon and rectum cancer samples than those of normal tissues." (PMID 39320349, 2024). "(E) Comparison of expression levels of CREB1 and HNF4A between native and tumor tissues in colon adenocarcinoma (COAD) and rectum adenocarcinoma (READ) tumors." (PMID 39320349, 2024).
cutaneous melanoma (3 papers, 2010 to 2022). A primary melanoma arising from atypical melanocytes in the skin. "Furthermore, evidence indicates that inherited abnormalities in CREB1 pigmentation‐related genes can not only increase the risk of cutaneous melanoma but also influence patient clinicopathological features." (PMID 35505885, 2022).
fibrosarcoma (3 papers, 2011 to 2022). A malignant mesenchymal fibroblastic neoplasm affecting the soft tissue and bone. "In human fibrosarcoma cells, CREB-1 and c-Jun were the cell-specific transcription factors involved in CRE binding in the RFC promoter." (PMID 21760912, 2011).
fibrosis (3 papers, 2010 to 2023). the formation of excess fibrous connective tissue in an organ or tissue in a reparative or reactive process. "Some of the most significantly activated canonical pathways included hepatic fibrosis/hepatic stellate cell activation (CD14, COL1A1, FGFR2, IGFBP3, MMP2, and TGFBR1), and p38 MAPK signaling pathways (CREB1, PLA2G2A, TGFBR1)." (PMID 20540791, 2010). "Some proteins of these genes have already been associated with pathophysiological processes in the kidney: in tubulointerstitial fibrosis (c-MYC, PTEN, STAT3, HIF-1α, PT53); podocyte injury (EGFR, PT53, CTNNB1, CREB1); epithelial-mesenchymal transition (PTEN); and glomerulosclerosis (DICER1, IL1β)." (PMID 37035314, 2023).
glomerulosclerosis (3 papers, 2020 to 2023). A hardening of the kidney glomerulus caused by scarring of the blood vessels. "In the early stage of DN, CREB1 increases the production of FN by binding to the promoter of the fibronectin gene, leading to the accumulation of FN, decreased glomerular sclerosis filtration, and renal tubulointerstitial fibrosis." (PMID 34164430, 2021).
Intellectual disability (3 papers, 2017 to 2024). "In the same family 2, Ube2a, whose human ortholog is mutated in intellectual disability, contained a putative CREB1 BD outside a CpG island." (PMID 39596581, 2024).
intracerebral hemorrhage (3 papers, 2019 to 2025). A cerebrovascular disorder characterized by bleeding into one or both cerebral hemispheres including the basal ganglia and the cerebral cortex. "Creb1 is involved in the mechanism of intracerebral hemorrhage by regulating inflammation and BBB disruption." (PMID 40002863, 2025).
medulloblastoma (3 papers, 2020 to 2023). A malignant, invasive embryonal neoplasm arising from the cerebellum. "Hereto, we performed knockdown of either CREB1, CREBBP, or EP300 in MED8A cells, an in vitro model for Group 3 medulloblastoma and subsequently determined their sensitivity to the chemotherapeutic agent Etoposide." (PMID 34373489, 2021).
nasopharyngeal carcinoma (3 papers, 2021 to 2024). A carcinoma arising from the nasopharyngeal epithelium. "Based on these findings, the FoxO1-miR-148a-5p-CREB1 axis is involved in STAT3-mediated regulation of SRGN and the promotion of nasopharyngeal cancer growth and metastasis, thereby confirming the role of STAT3 in the proliferation, invasion, and anti-apoptotic effects of NPC cells." (PMID 36313702, 2022).
Neurodegeneration (3 papers, 2013 to 2019). Progressive loss of neural cells and tissue. "Other than the potential candidate genes, the compact SPNW also included many significant connecting proteins like APP, BACE1, CCNA2, CREB1, E2F1, EGR1 and MDM2 which were previously implicated to play critical roles in many neurodegeneration disease pathogenesis including Alzheimer’s." (PMID 26784894, 2016). "The compact shortest path network included many noteworthy connecting proteins like APP, CREB1, HSP90AA1, MAPT and PTEN which were previously implicated to play critical roles in many neurodegeneration disease pathogenesis and couple of them were indicated to have neuroprotective mechanism." (PMID 24688734, 2013).
papillary thyroid carcinomas (3 papers, 2012 to 2022). "The increased activity of CREB1 in papillary thyroid carcinomas has been already documented by high levels of pS133-CREB1." (PMID 23145146, 2012).
rectal cancer (3 papers, 2020 to 2025). A primary or metastatic malignant neoplasm that affects the rectum. "The combination of ASCC3 with several immune-related genes, including JAK1, NFKB1, SEMA5A, NR2C2, CNTF and CREB1, plays a significant predictive role in the prognosis of rectal cancer patients." (PMID 40881169, 2025). "Additionally, our diagnostic and prognostic models, constructed using machine learning, highlight the significant predictive value of ASCC3 in combination with various immune-related genes, including JAK1, NFKB1, SEMA5A, NR2C2, CNTF and CREB1, for rectal cancer prognosis." (PMID 40881169, 2025).
renal carcinoma (3 papers, 2015 to 2024). A carcinoma arising from the epithelium of the renal parenchyma or the renal pelvis. "On the opposite, CREB-1 activation together with mTOR inhibitors has also been described to potentiate chemotherapies in renal cancers." (PMID 26474850, 2015).
renal cell carcinoma (3 papers, 2016 to 2020). "However, CREB1 expression and underlying control mechanisms are only poorly analyzed in renal cell carcinoma (RCC)." (PMID 32300145, 2020).
respiratory failure (3 papers, 2011 to 2016). The significant impairment of gas exchange within the lungs resulting in hypoxia, hypercarbia, or both, to the extent that organ tissue perfusion is severely compromised. "Likewise, a recent study demonstrated that Creb1-/- mice died from respiratory failure after birth." (PMID 22096492, 2011).
retinal degeneration (3 papers, 2013 to 2024). Degeneration of the retina. "While down-regulation of CREB1 has been related to PR cell death in mouse models of retinal degeneration, an increase in the levels of native CREB1 has been reported in the rcd1 dog." (PMID 24581223, 2014).
age-related macular degeneration (2 papers, 2015 to 2021). Age-related loss of vision in the central portion of the retina (macula), secondary to retinal degeneration. "Increased phosphorylation of CREB in the brain was observed in two rat models of ischemic preconditioning and Creb1 expression was detected in canine and human retinas affected with age-related macular degeneration (AMD)." (PMID 25902940, 2015).
bone fibrous dysplasia (2 papers, 2021 to 2023). "It was also shown that miR-181a-5p regulates c-AMP response element-binding protein (CREB)-1 and might also participate in a feedback loop with CREB1-regulating miR-181a-5p in bone fibrous dysplasia." (PMID 36769196, 2023).
colonic diseases (2 papers, 2017 to 2021). "Inherently, CREB1 is a transcription factor of the basic leucine zipper family that exerts an anti-inflammatory role in colonic diseases, including UC." (PMID 34895044, 2021).
colorectal tumor (2 papers, 2016 to 2022). "As examples, the LEF1-AS1 expression could be induced by CREB1, and the high expression of LEF1-AS1 promoted tumorigenesis of colorectal tumor through sponging miR-489 and stabilizing DIAPH1." (PMID 35371339, 2022).
developmental delay (2 papers, 2019 to 2024). "Moreover, de novo deletion within CREB1 was observed in a girl with developmental delay, autistic traits and Rett-like features." (PMID 31649562, 2019).
melasma (2 papers, 2020 to 2025). "The potential mechanism of PE extract against melasma was predicted to target the CREB1/MITF/TYR/DCT axis." (PMID 40369904, 2025). "Pearl can alleviate melasma by targeting the CREB1/MITF axis and then the melasma‐related gene loci TYR and DCT." (PMID 40369904, 2025). "CAMP‐responsive element binding protein 1 (CREB1) was the target of pearl against melasma." (PMID 40369904, 2025).
ovarian serous cystadenocarcinoma (2 papers, 2020). A malignant serous cystic epithelial neoplasm arising from the ovary. "Evaluating The Cancer Genome Atlas (TCGA) data using the cBioPortal database, showed only low numbers (with the exception of neuroendocrine prostate cancer: 12%) of genetic alterations for CREB1 (e.g. gene amplification) ranging from 1.3% in ccRCC to 5% in ovarian serous cystadenocarcinoma." (PMID 32300145, 2020). "Pearson correlation analysis showed that EGFR (R = 0.16, P = 0.00072), PTEN (R = 0.098, P = 0.043), SIRT1 (R = 0.094, P = 0.013), RELA (R = 0.18, P = 0.00013) and CREB1 (R = 0.16, P = 0.00094) were significantly correlated with LDHAP5 expression in ovarian serous cystadenocarcinoma." (PMID 32536817, 2020).
peripheral vascular disease (2 papers, 2019). Any disorder affecting blood flow through the veins or arteries outside of the heart. "As current treatments for peripheral vascular diseases in humans are limited in effectiveness, this JNK3–Foxo3a–Egr1/Creb1 pathway may serve as a promising target for therapies aiming to improve the peripheral vasculature in diabetic and other affected patient populations." (PMID 31530804, 2019).